LIFR (LIF receptor subunit alpha)
Description:
[Isoform 1]: Functions as a membrane-bound signal-transducing subunit either in complex with IL6ST/gp130 or as part of the ciliary neurotrophic factor receptor (CNTFR) complex composed by CNTFR, IL6ST/gp130 and LIFR. Signal transmission is initiated either by binding directly to cytokines, such as OSM or LIF or CTF1, or through the binding of other cytokines, like CNTF, CLCF1 or the heterodimeric complex CRLF1-CLCF1 to the non-signaling receptor CNTFR; ligand binding induces heterodimerization of IL6ST/gp130 and LIFR which activates JAK tyrosine kinases bound to their intracellular domains. These kinases subsequently phosphorylate the homodimer or heterodimer form of IL6ST/gp130. The tyrosine phosphorylated signaling receptors serve in turn as docking sites for recruitment and activation of signal transducer and activators of transcription (STATs). Engages sites 3 of ligands cytokines. [Isoform 2]: Could inhibit the biological activity of LIF by blocking its binding to receptors on target cells.
Synonyms: LIF-R; CD118; SJS2; STWS; SWS
Tractability: Antibody: its Gene Ontology location is reachable by antibodies, with high confidence; UniProt places it where antibodies can reach, with medium confidence; UniProt predicts a signal peptide or a membrane-spanning region. PROTAC: ubiquitination databases record sites on it.
Target class: Membrane receptor
Gene: Protein-coding gene on chromosome 5 (38,474,668 to 38,608,354, reverse strand). Ensembl gene ENSG00000113594.
Subcellular location: Cell membrane (Isoform 1); Secreted (Isoform 2)
Pathways (Reactome):
Gene expression (Transcription): RUNX1 regulates transcription of genes involved in interleukin signaling
Immune System: IL-6-type cytokine receptor ligand interactions
Gene Ontology:
Molecular function: ciliary neurotrophic factor receptor activity; ciliary neurotrophic factor receptor binding; coreceptor activity; cytokine activity; cytokine receptor activity; growth factor binding; leukemia inhibitory factor receptor activity; oncostatin-M receptor activity; protein binding; cytokine binding
Biological process: cell population proliferation; ciliary neurotrophic factor-mediated signaling pathway; cytokine-mediated signaling pathway; leukemia inhibitory factor signaling pathway; oncostatin-M-mediated signaling pathway; positive regulation of cell population proliferation; response to cytokine; cell surface receptor signaling pathway
Cellular component: ciliary neurotrophic factor receptor complex; extracellular exosome; receptor complex; external side of plasma membrane; plasma membrane; extracellular region; membrane
Genetic constraint (gnomAD): Loss-of-function variants: 48 observed, 76.49 expected, observed/expected ratio (o/e) 0.63, 90% interval 0.5 to 0.8. The upper end of that interval is the gene's LOEUF score, 0.8, which puts it in group 3 of 6, group 1 being the genes least tolerant of losing a copy. Missense variants: 893 observed, 957.02 expected, observed/expected ratio (o/e) 0.93, 90% interval 0.88 to 0.99. Synonymous variants: 280 observed, 320.81 expected, observed/expected ratio (o/e) 0.87, 90% interval 0.79 to 0.96.
Cancer hallmarks: invasion and metastasis (suppresses); invasion and metastasis; invasion and metastasis (promotes)
Homologues: Orthologues: chimpanzee LIFR (99% identical), macaque LIFR (97% identical), dog LIFR (86% identical), pig LIFR (86% identical), guinea pig LIFR (83% identical), rabbit LIFR (79% identical), mouse Lifr (75% identical), rat Lifr (74% identical), tropical clawed frog lifr (44% identical), zebrafish osmr (19% identical). Paralogues in human: OSMR (25% identical), IL12RB2 (14% identical), IL6ST (14% identical), CSF3R (13% identical), LEPR (11% identical), IL31RA (11% identical), IL27RA (9% identical), IL23R (9% identical), IL12RB1 (8% identical), PRLR (7% identical), CRLF1 (7% identical), GHR (6% identical), and 11 more.
Diseases named in the same sentence as LIFR in open-access papers:
LIFR is named in the same sentence as 148 diseases in open-access papers, as found by Europe PMC text mining. Sharing a sentence is not in itself a finding about the gene and the disease. The quoted sentences say what the papers report.
breast cancer (81 papers, 2007 to 2026). A primary or metastatic malignant neoplasm involving the breast. "Dysregulation of the leukemia inhibitory factor receptor (LIFR)-STAT3-SOCS3 signaling pathway leading to pSTAT3 negativity has been associated with metastatic potential in breast cancer." (PMID 32850390, 2020). "This antitumorigenic role is underlined by the fact that LIFR is less expressed in breast cancer tissues compared to normal breast tissues." (PMID 32245259, 2020). "An analysis of human breast cancer samples with or without aggressive colonization of the bone revealed that nPAK4 expression was significantly associated with ERα+ as well as LIFR and breast cancer with bone metastasis that often leads to a poorer prognosis." (PMID 30177834, 2019). "Activation of YAP through the loss of leukemia inhibitory factor receptor (LIFR) promotes metastatic colonization of breast cancer cells." (PMID 30805310, 2019). "Loss of LIF receptor (LIFR) of breast cancer DTCs in turn promoted their outgrowth from quiescence and down-regulated CSC associated genes." (PMID 30258818, 2018). "Another study published at that time also found that activation of YAP, in this case through loss of Leukemia Inhibitory Factor Receptor (LIFR), promoted metastatic colonization of breast cancer cells." (PMID 29642615, 2018). "In one of our previous studies using a rat model, we showed a downregulation of LIFR expression in mammary epithelial stem cells from a high risk group (nulliparous) compared to a low risk group (parous) for breast cancer occurrence." (PMID 25962054, 2015). "The preceding analysis suggests a transcriptomic pattern downstream of FAM3C/LIFR/STAT3 modulation that is specifically implicated in mammary carcinoma pathology and that is exemplified by changes in the regulation of an established mediator of EMT and cell fate, TWIST1." (PMID 37927213, 2023). "Additionally, gene ontology analysis was performed using the DAVID Knowledgebase, revealing a significant association between the shPCBP1/FAM3C/LIFR transcriptomic signature and phenotypic context involved in mammary carcinoma pathology." (PMID 37927213, 2023). "Moreover, induction of STAT3 activation caused by leukemia inhibitory factor receptor (LIFR) leads to resistance to Trastuzumab-emtansine (T-DM1) in breast cancer." (PMID 34488773, 2021). "LIFR/STAT3 axis, expressed in breast cancer cells, has been implicated in maintaining dormancy within the bone niche." (PMID 41596432, 2026). "The nuclear PAK4-Erα-LIFR axis facilitates bone metastasis of ER+ breast cancers by initiating an EMT program, where high expression of nPAK4 is often associated with a poorer prognosis." (PMID 40977686, 2025). "Our study extends this paradigm by demonstrating that breast cancer-derived exosomal miR-221-3p remotely disrupts the brain vascular niche via LIFR-mediated glycolytic activation and tight junction impairment." (PMID 41272827, 2025). "In ER+ breast cancers, nuclear p21-activated kinase 4 (nPAK4) targets LIFR, augmenting the PAK4-ER axis-mediated bone metastases, and functions as a novel repressor of ERα-mediated transactivation, operating in an E2-dependent manner." (PMID 40977686, 2025). "Use of histone deacetylase inhibitors (HDACi) in breast cancer, can induce LIFR and consequently pro-dormancy mechanisms." (PMID 41091336, 2025). "In contrast, miR-125a-5p inversely induced the expression of TAZ in breast cancer cells by suppressing leukemia inhibitory factor receptor (LIFR), an inhibitor of YAP and TAZ activity that raises the fraction of stem cells in cancer." (PMID 37692482, 2024). "For example, HDACis have been shown to epigenetically induce the leukemia inhibitory factor receptor (LIFR), which promotes dormancy in breast cancer cells, and activate a pro-dormancy program in breast cancer." (PMID 39682769, 2024). "Leukemia inhibitory factor (LIF) and its receptor LIFR provide a pro-dormancy signal to metastasized breast cancer cells in bone." (PMID 39682769, 2024).
breast cancer (continued). "miR-9 enhances metastasis by targeting the tumor suppressor gene E-cadherin and LIFR,13,117 especially in breast cancer cells." (PMID 37692482, 2024). "Under E2 stimulation, PAK4 forms a complex with ERα, which is recruited to the target gene LIFR of ERα, downregulating LIFR expression and promoting the metastasis and invasion of breast cancer cells." (PMID 38041134, 2023). "Depletion of one subunit of the LIF receptor (LIFR), specifically gp190, has been found to be associated with increased metastatic processes in a breast cancer model in conjunction with a deficient Hippo pathway." (PMID 38137514, 2023). "Following shRNA knockdown of FAM3C in human cell lines, qPCR analysis revealed a measurable loss of LIFR mRNA levels relative to control cells, demonstrating a correlation between LIFR and FAM3C expression in human mammary carcinoma." (PMID 37927213, 2023). "Given the role of PCBP1 in our mouse model of mammary carcinoma and the increase in FAM3C and LIFR expression following loss of PCBP1, we sought to identify the mechanism(s) governing LIFR expression in mammary epithelium." (PMID 37927213, 2023). "Specific inhibition of LIF/LIFR interactions has been proposed as a promising target for breast cancer therapy." (PMID 35163731, 2022). "In spite of the data indicating the pro-oncogenic role of LIF, a whole genome RNAi screening identified LIFR as a mammary tumor suppressor." (PMID 35163731, 2022). "For treatment of solid tumors, such as breast cancer, the efficacy of histone deacetylase inhibitors (HDACs) has been suggested to be limited by LIFR expression induction and the consequent pro-oncogenic activation of the JAK/STAT3 signaling pathway." (PMID 35163731, 2022). "Other downstream genes of miR-21-5p have also been reported in human diseases, such as SFRP5 in non‐alcoholic steatohepatitis, SMAD7 in lung cancer, PDCD4 in breast cancer, and LIFR in gastric cancer." (PMID 35549815, 2022). "Our examination validated the role of LIFR signaling in describing the cancer stemness characteristics in breast cancer cells." (PMID 34947829, 2021). "But LIF does not seem to be solely dependent on STAT3 activation in order to be pro-oncogenic, and some have even pointed to tumor cell dormancy induction via a LIF : LIFR : STAT3 axis in breast cancer to bone marrow metastasis." (PMID 34395259, 2021). "Our study showed that CAFs secrete LIF to stimulate the LIF receptor on breast cancer cells and thus activate the LIF/LIFR signaling pathway, which promotes breast cancer stemness in vitro." (PMID 34947829, 2021). "We identified 4 mRNAs (TPD52, BTG2, CCND2, LIFR) involved in the prognosis of breast cancer using survival analysis." (PMID 34545330, 2021). "Intriguingly, in breast cancer, anti-metastatic potential has been attributed to LIFR, as LIFR downregulation was responsible for the pro-metastatic effect of the E-cadherin suppressor miR-9." (PMID 34361105, 2021). "Activation of JAK1-STAT3 signaling decreases drug responsiveness in breast cancer by upregulating LIFR." (PMID 34947829, 2021). "Using the LIFR inhibitor antibody revealed that blocking the LIFR is a sufficient way to inhibit the dedifferentiation of breast cancer cells." (PMID 34947829, 2021). "Part of the signaling pathway, at least in breast cancer cells, involves the leukemia inhibitory factor receptor (LIFR) and signal transducer and activator of transcription 3 (STAT3) signaling." (PMID 33596971, 2021). "The leukemia inhibitory factor receptor (LIFR) is a breast cancer metastasis suppressor that functions upstream of Hippo signaling." (PMID 34831147, 2021). "It was observed that Nanog and Oct4 expression, which was substantially increased after LIF or CAF-CM treatment, was decreased following exposure to the LIFR inhibitor antibody in both breast cancer cell lines." (PMID 34947829, 2021).
breast cancer (continued). "Based on previous findings in endometriosis linking MSI proteins to LIFR expression we aimed to investigate this interplay in breast cancer." (PMID 32245259, 2020). "Recently, the interleukin-like epithelial-mesenchymal transition (EMT) inducer (ILEI) has emerged as a new cytokine that can activate STAT3 and drive both EMT and breast cancer stem cell formation through LIFR." (PMID 32023849, 2020). "In this study, we investigated the consensus of LIF and LIFR immunization on the growth of mouse mammary tumors." (PMID 32651426, 2020). "In another study, a signature of four immune-related genes (APOD, CXCL14, IL33, and LIFR) was correlated with breast cancer prognosis." (PMID 33092068, 2020). "For the first time, we identified a role function of the nuclear PAK4 in promoting the breast-to-bone metastasis of ERα+ breast cancer via PAK4–ERα-LIFR axis." (PMID 30177834, 2019). "Mechanistically, nPAK4 promoted the metastasis of ERα-positive breast cancer cells by targeting LIFR, a bone metastasis suppressor." (PMID 30177834, 2019). "The levels of LIFR are lower with bone metastases and are significantly and inversely correlated with patient outcomes in breast cancer patients." (PMID 30177834, 2019). "CXCL14 and LIFR are associated with the prognosis of Luminal A, HER-2 positive breast cancer and TNBC." (PMID 31781173, 2019). "Recently, one of the ERα downstream target gene, LIFR has been shown to suppress breast cancer bone metastasis." (PMID 30177834, 2019). "Differential expression of LIF and/or LIFR is reported in a number of cancers including breast cancer, colorectal cancer (CRC), NPC, osteosarcoma, pancreatic cancer, melanoma, cholangiocarcinoma and cervical cancer." (PMID 30263091, 2018). "LIFR expression has previously been identified in breast cancer, CRC, gastric cancer, liver cancer and pancreatic cancer." (PMID 30263091, 2018). "Remarkably, two recent reports have highlighted LIFR as a novel metastasis suppressor in breast cancer." (PMID 28629464, 2017). "Increased LIFR activity has also been correlated with a reduction in the pool of breast cancer stem cells." (PMID 27144453, 2016). "LIFR downregulation is involved in the induction of cell migration, invasion and metastatic colonization of breast cancer cells and LIFR presence is important for maintenance of pluripontecy of embryonic cells." (PMID 26809067, 2016). "LIFR is a breast cancer metastasis suppressor upstream of the Hippo-YAP pathway and a prognostic marker." (PMID 26087655, 2015). "It has been shown that LIFr inhibits breast cancer metastasis by inactivating the activity of the transcriptional co-activator YAP." (PMID 26329521, 2015). "We further demonstrated that miR-125a influenced stem cells by regulating Hippo signaling through LIFR in human primary breast cancer cells confirming the data obtained from established cell lines." (PMID 25962054, 2015). "Analyses of human normal breast tissues and breast cancer tissues showed lower expression levels of LIFR at both the transcript and protein levels in breast cancer tissues compared to normal breast tissues." (PMID 25962054, 2015). "LIFR is a known tumor/metastatic suppressor for breast cancer and its downregulation in breast cancer has been demonstrated." (PMID 25962054, 2015). "This suggests that nPAK4 may modulate the dormancy or CSC-like phenotype in breast cancers through LIFR, representing a potential target or novel tumor marker in cancer therapy." (PMID 40977686, 2025). "Highly invasive breast cancer-derived exosomal miR-221-3p induced glycolysis and lactic acid accumulation in brain microvascular endothelial cells by targeting the leukemia inhibitory factor receptor (LIFR), leading to endothelial barrier destruction and reduced tight junction protein expression." (PMID 41272827, 2025).
breast cancer (continued). "In a study that aimed to understand the molecular basis of why HDACi respond poorly in solid tumours, the authors found that in breast cancer cells, the feedback activation of the leukemia inhibitory factor receptor (LIFR) signaling, limited the response to HDACi." (PMID 40011240, 2025). "On the other hand, high LIFR expression has been correlated with tumor progression, and inhibition of LIFR improves histone deacetylase (HDAC) inhibitor efficacy, suggesting that further research is needed to elucidate the role of LIF and LIFR in breast cancer." (PMID 40507264, 2025). "We previously demonstrated that PTHrP localizes to the proximal promoter region and downregulates breast cancer cell expression of leukemia inhibitory factor receptor (LIFR), which is a known breast tumor dormancy regulator in bone, breast tumor suppressor, and lung metastasis suppressor." (PMID 38409028, 2024). "In addition to TMEM41B, we identified LIFR among the potential targets of miR-660-5p, which has previously been reported as a tumor suppressor in breast cancer metastasis." (PMID 39709500, 2024). "LIFR is down-regulated in human breast cancer and is inversely connected with metastasis." (PMID 37692482, 2024). "LIFR signaling activates multiple downstream signaling pathways in breast cancer, including ERK." (PMID 38409028, 2024). "In our studies, pharmacologic LIFR inhibition revealed an unexpected trend whereby breast cancer cells treated with the inhibitor had significantly elevated phosphorylated p38 and a p38/ERK signaling ratio compared to vehicle treated cells, regardless of PTHrP mutant expression." (PMID 38409028, 2024). "Additionally, in breast cancer cells, miR-125a regulates stem cells through Hippo signaling suppression by LIFR." (PMID 37692482, 2024). "Furthermore, HDAC inhibitors stimulated LIFR expression in breast cancer cells and reduced proliferation rates." (PMID 36925915, 2023). "ILEI has been shown to act via the LIFR/ STAT3 axis to mediate EMT in breast cancer stem cells." (PMID 37226685, 2023). "LIFR had been previously identified as a suppressor of breast cancer and metastasis." (PMID 36925915, 2023). "Studies have detected the decreased expression level of LIFR and identified the tumor suppressor role of LIFR in different tumor types, such as liver cancer, breast cancer, gallbladder cancer, gastric cancer, lung cancer, pancreatic cancer, clear cell renal cell carcinoma, and colorectal cancer." (PMID 36925915, 2023). "Therefore, combining HDAC with JAK1 or BRD4 (which is recruited at LIFR gene promoter in cells under HDAC treatment) blockers has been proposed for breast cancer treatment." (PMID 35163731, 2022). "Besides, LIFR has been shown to be downregulated in patients with poorer prognosis among a cohort of breast cancer patients with bone metastasis." (PMID 35163731, 2022). "Other negatively correlated validated targets for miR‐21‐5p included the mRNAs of LIFR, a metastasis suppressor in breast cancer, and SPRY2, a negative regulator of RAS and MAPK signalling, with Pearson correlations of −0.46 and −0.42, respectively (P = 4.9e − 60 and 5.4e − 48)." (PMID 35182081, 2022). "On the other hand, a loss of LIFR in nonmetastatic breast cancer cells results in the activation of YAP, which promotes migration, invasion and metastatic colonization." (PMID 34831147, 2021). "Our results suggest that targeting LIF/LIFR signaling might be a potent therapeutic strategy for breast cancer and the prevention of tumor recurrence." (PMID 34947829, 2021). "We indicated the significant role of the LIF/LIFR pathway as a regulator of breast cancer stemness." (PMID 34947829, 2021). "The dysregulation of LIFR influences the development of prostate cancer and breast cancer." (PMID 34545330, 2021). "Furthermore, the effect of LIF protein on the dedifferentiation process of breast cancer cells to breast cancer stem cells through the LIF/LIFR pathway is studied." (PMID 34947829, 2021).